TFEB (transcription factor EB)
Diseases named in the same sentence as TFEB in open-access papers (continued):
Sharing a sentence is not in itself a finding about the gene and the disease.
pancreatic cancer (29 papers, 2016 to 2025). "For instance, data from the Human Protein Atlas demonstrate that low TFEB expression is associated with poor survival rates in renal and pancreatic carcinomas." (PMID 40083935, 2025). "Notably, increased proliferation in pancreatic cancer cells is associated with TFEB overactivation, providing an excess of nutrients obtained by the glycogen synthase kinase-3 (GSK3) inhibitors." (PMID 31569540, 2019). "For instance, transcription factor EB (TFEB) K91la inhibits the interaction with WW domain containing E3 ubiquitin protein ligase 2 (WWP2) in pancreatic cancer cells." (PMID 40994548, 2025). "For instance, TFEB K91la disrupts its interaction with E3 ubiquitin ligase WWP2, lowering TFEB ubiquitination and proteasomal degradation in pancreatic cancer." (PMID 40994548, 2025). "We therefore investigated the expression of MITF, TFE3, and TFEB by immunohistochemistry (IHC) across pancreatic tumor types." (PMID 41310888, 2025). "In this study, we demonstrated that TFEB in pancreatic cancer cells (PCCs) regulates the BCAA metabolism pathway, which is essential for cell proliferation and metastasis, by regulating BCAT1, a key enzyme in BCAA metabolism." (PMID 38938061, 2024). "Both in vivo and in vitro experiments showed that TFEB plays an important role in the proliferation and metastasis of pancreatic cancer." (PMID 38938061, 2024). "IHC staining and combined prognostic analysis of clinical samples from patients with pancreatic cancer revealed that patients with double positivity (high expression) for TFEB and BCAT1 tended to have a poorer prognosis." (PMID 38938061, 2024). "In pancreatic cancer, the transcription factor EB (TFEB) is required to sustain GLS-dependent glutamine catabolism; therefore, it has been proposed as a new potential therapeutic target." (PMID 38542254, 2024). "The survival and progression of pancreatic cancer depend on autophagy; therefore, the role of TFEB, a key regulator of autophagy, in cancer progression and regulation has been widely studied." (PMID 38938061, 2024). "The expression of TFEB in almost all pancreatic cancer cell lines was higher than that in normal pancreatic H6C7 cells." (PMID 38938061, 2024). "In pancreatic duct adenocarcinoma (PDA) cell lines, TFEB nuclear localization is increased, and TFEB expression is higher in human pancreatic cancer samples than in normal tissue samples." (PMID 38365838, 2024). "The results showed that the average expression of TFEB in 179 pancreatic cancer tissues was significantly higher than that in 171 adjacent tissues." (PMID 38938061, 2024). "Our clinical samples also showed high expression of TFEB in pancreatic cancer, which is in line with the conclusions obtained from the analysis of data from TCGA and GTEx databases." (PMID 38938061, 2024). "TGF-β induces the TFEB expression via the canonical Smad pathway in Smad4-positive cells and facilitates TFEB-mediated autophagic activation in pancreatic cancer cell lines." (PMID 39519229, 2024). "The results showed that TFEB, which is generally highly expressed in pancreatic cancer, promoted the proliferation and metastasis of PCCs." (PMID 38938061, 2024). "GSK-3 inhibition leads to TFEB dephosphorylation, which correlates with TFEB dislocation from 14-3-3 chaperones and TFEB nuclear localization in the pancreatic cancer cell." (PMID 37366889, 2023). "This was despite pancreatic cancer cells already displaying some extent of TFEB nuclear localization under basal conditions as previously reported." (PMID 36746928, 2023). "Consistently, in pancreatic ductal adenocarcinoma, TFEB suppression limited autophagy and attenuated gemcitabine resistance in pancreatic cancer cells." (PMID 37305393, 2023). "TFEB-driven autophagy has been proven to potentiate TGF-β induced migration in pancreatic cancer cells." (PMID 37885995, 2023).
pancreatic cancer (continued). "Our immunoblot and immunofluorescence results confirmed that SDS-203 treatment translocates the TFEB into the nucleus of pancreatic cancer cells." (PMID 35322026, 2022). "TFEB gene silencing results in a significant decrease in the hyperproliferative phenotype and progression of pancreatic carcinoma to advanced stages." (PMID 35970822, 2022). "Pancreatic cancer cells show a significantly elevated TFEB expression compared with normal tissue samples." (PMID 33513833, 2021). "The expression of TFEB was found to be higher in pancreatic cancer samples compared with normal tissue samples." (PMID 33513833, 2021). "In our present study, we demonstrate that pancreatic cancers have high levels of TFEB, and that this is indispensable for their growth." (PMID 33513833, 2021). "While survival data was not available in the prior study, a recent study found significantly elevated levels of transcription factor EB (TFEB) protein in pancreatic cancer specimens relative to adjacent healthy tissue." (PMID 34503118, 2021). "We found downregulation of miR-29 in a range of pancreatic cancer cell lines, and restored expression of miR-29a blocked autophagy flux by inhibiting expression of key autophagy proteins, TFEB and ATG9A." (PMID 27626694, 2016). "Consistently, we observed higher ATG9A and TFEB expression in pancreatic cancer cells that have low miR-29a expression (Panc-1 and MIA PaCa-2), compared to normal pancreatic epithelial cell line (HPNE) and cancer cell line with high miR-29 expression (AsPC-1)." (PMID 27626694, 2016). "In our western blot analysis, overexpression of miR-29a in pancreatic cancer cells resulted in a marked downregulation of both TFEB and ATG9A expression." (PMID 27626694, 2016). "TFEB activation induced autophagy and facilitated the progression of pancreatic cancer." (PMID 37305393, 2023). "A similar role for TFEB has been reported in regulating glutamine metabolism in pancreatic cancer." (PMID 37160873, 2023). "Lactylation at the Lys91 site of TFEB inhibits its interaction with WWP2, stabilising TFEB by obstructing WWP2-mediated proteasomal degradation pathways and thereby promoting autophagy in pancreatic cancer." (PMID 41463025, 2025). "To investigate the effect of high TFEB expression on the biological behaviour of pancreatic cancer cells, we transfected PANC‐1 and CFPAC‐1 cells with two TFEB shRNAs." (PMID 38938061, 2024). "To explore the relation between TFEB and pancreatic cancer, we used the UCSC‐XENA database to determine the TFEB expression levels in pancreatic cancer and adjacent tissues." (PMID 38938061, 2024). "However, the regulatory mechanisms of TFEB in pancreatic cancer remain unclear." (PMID 38938061, 2024). "In this study, we focused on transcription factor EB (TFEB), a key factor in the regulation of autophagy, to explore its effect on the phenotype and role in the unique amino acid utilisation pattern of pancreatic cancer cells (PCCs)." (PMID 38938061, 2024). "TFEB, a key regulator of autophagy, reprograms the metabolism of BCAAs by transcriptionally regulating the BCAT1 and thus influences pancreatic cancer progression." (PMID 38938061, 2024). "Our study showed that pancreatic cancer cells treated with SDS-203 triggered an incomplete autophagic response and a nuclear translocation of transcriptional factor TFEB." (PMID 35322026, 2022). "However, the precise roles of TFEB in pancreatic cancer growth remain unclear." (PMID 33513833, 2021). "This was reversed by the addition of the BCAAs metabolite BCKAs, which also proved that the BCAA metabolic pathway is key to TFEB‐mediated cell cycle changes and cell proliferation in pancreatic cancer rather than other pro‐cancer signalling pathways." (PMID 38938061, 2024). "Besides, we explored the relationship between TFEB/BCAT1 expression and the clinicopathological features of pancreatic cancer." (PMID 38938061, 2024).
pancreatic cancer (continued). "For example, the combined use of EO, a TFEB inhibitor based on BCAA dietary restriction, provides a new direction for targeting novel therapeutic modalities, such as metabolic reprogramming, in pancreatic cancer." (PMID 38938061, 2024). "Notably, TFEB and TFE3 expression levels are increased in pancreatic cancer, compared with normal pancreatic tissues." (PMID 36746928, 2023). "Considering the known role of TFEB as a master regulator of the lysosomal-autophagy pathway, and the recent evidence indicating that activation of autophagy driven by MiT/TFE genes plays an important role in pancreatic cancer, we tested whether autophagy plays a role in TFE-tRCC development." (PMID 27668431, 2016).
Huntington disease (23 papers, 2015 to 2024). Huntington disease (HD) is a rare neurodegenerative disorder of the central nervous system characterized by unwanted choreatic movements, behavioral and psychiatric disturbances and dementia. "Moreover, defective autophagic flux caused by low levels of TFEB has been linked to the development of Alzheimer’s, Parkinson’s, and Huntington’s diseases." (PMID 33981707, 2021). "Interestingly, TFEB activation has been shown to reduce the accumulation of the pathogenic protein in a cellular model of Huntington's disease (HD) and a mouse model of Parkinson's disease (PD), which was achieved by gene transfer through viral vectors." (PMID 27433468, 2016). "Secretory carrier membrane protein 5 (SCAMP5) is a membrane protein induced in the brains of Huntington’s disease patients and its expression is regulated by transcription factor EB (TFEB), a transcriptional regulator of autophagy." (PMID 38525704, 2024). "Recently, it was reported that PGC‐1α can robustly induce the expression of TFEB and rescue proteotoxicity in a mouse model of Huntington's disease." (PMID 32667742, 2020). "TFEB is expressed during aberrant lysosomal conditions like in lysosomal storage diseases (LSDs), amyloid diseases (Alzheimer’s, Lewy Body dementia), and Huntington’s disease." (PMID 29209494, 2017). "In neurons from models of both Huntington's disease and Kennedy's disease, expanded polyQ tracts in mHtt or mAR are able to bind and sequester the disordered Gln‐rich N‐terminus of TFEB, and disrupt its ability to upregulate the ATGs, perhaps by impairing phase separation." (PMID 37728021, 2023). "Here we show that SCAMP5, a secretory carrier membrane protein significantly induced in the brains of Huntington's disease patients, is quickly and transiently induced by protein stress and autophagic stimulation, and is regulated by the master autophagy transcriptional regulator TFEB." (PMID 28700687, 2017). "At least in an in vivo model of Huntington’s disease (HD), PGC-1α overexpression ameliorated the neurodegeneration phenotype through TFEB activation." (PMID 35842725, 2022). "TFEB and PGC-1α cooperatively regulate lysosomal activity and lipid catabolism in Huntington’s disease mice model and under starvation." (PMID 26244551, 2015). "Moreover, in Huntington’s disease and Neuro2a cells PGC-1α places an upstream of TFEB in the transcriptional regulation of the autophagy-lysosome pathway." (PMID 33714196, 2021). "Notably, Tem (10 μM, 6 h) also induced dramatic TFEB nuclear translocation in multiple disease fibroblasts, including NPC fibroblasts, Huntington disease (HD) fibroblasts, and immortalized Duchenne Muscular Dystrophy (DMD) myoblasts." (PMID 31112550, 2019). "More importantly, Tsunemi’s laboratory revealed that PGC-1α rescues Huntington’s disease proteotoxicity by promoting the transactivation of TFEB, a master regulator of the autophagy-lysosome pathway, suggesting that PGC-1α may activate autophagy through a TFEB-dependent mechanism." (PMID 33714196, 2021).
steatosis (23 papers, 2019 to 2026). Increased lipid within the cytoplasm of cells. "Upon 2 weeks WD challenge, hepatic PANK1-deficient mice developed worsened steatosis with ~2-fold higher hepatic triglyceride (TG) and cholesterol content than controls, which could be prevented by TFEB overexpression." (PMID 36171419, 2022). "A recent study demonstrated that in a MASH mouse model, an SGLT2 inhibitor increased hepatic autophagic flux via AMPK–TFEB (transcription factor EB) activation, while simultaneously decreasing steatosis, inflammation, and fibrosis." (PMID 41545323, 2026). "We found that TFEB activation in KCs enhanced their ability to metabolize lipids from hepatocytes, and this resulted in reduced steatosis and liver injury." (PMID 41665896, 2025). "The nuclear levels of TFEB were inversely correlated with the steatosis scores of liver biopsy samples from NAFLD patients." (PMID 41390431, 2025). "TFEB knockdown substantially blocked the curative effect of hUC-MSCs on steatosis, as indicated by increased lipid droplets, elevated TG content, and upregulated expression of lipid metabolism-associated proteins FASN and SREBP1c." (PMID 41390431, 2025). "It has been reported that nuclear TFEB expression is inversely correlated with the steatosis severity of liver biopsy samples from NAFLD patients." (PMID 41390431, 2025). "Overexpression of TFEB promotes autophagosome lysosome biogenesis, thereby inhibiting ethanol induced liver injury and steatosis in mice." (PMID 39758315, 2024). "In contrast, overexpression of TFEB increases the biogenesis of lysosomes and prevents ethanol-induced steatosis and liver injury." (PMID 37021975, 2023). "While results with Atg7-Li KO seem conflicting, TFEB genetic modulation experiments in the literature are apparently more consistent toward a protective role against steatosis." (PMID 33937257, 2021). "Crucially, the beneficial impact of liraglutide on steatosis was hindered by TFEB downregulation." (PMID 38978979, 2024). "Furthermore, the upregulation of pro-autophagic transcription factors such as FoxO1 and transcription factor EB (TFEB) prevented steatosis." (PMID 35887082, 2022). "Moreover, thioredoxin interacting protein (TXNIP/VDUP1) mediates the activation of AMPK, inhibition of mTOR, and nuclear translocation of TFEB which ultimately resulted MCD diet-induced steatosis, inflammation, and fibrosis." (PMID 34711912, 2021). "In addition, the use of TFEB agonists has recently been the focus of a study based on the demonstration that TFEB overexpression in hepatocytes protects against steatosis and insulin resistance via autophagy in mice fed on a high-fat diet." (PMID 32244266, 2020). "Given that TFEB plays a critical role in the regulation of autophagy and lysosome biogenesis, we evaluated whether liraglutide alleviated steatosis by promoting TFEB-dependent lysosome biogenesis in vivo and in vitro." (PMID 33330497, 2020). "Mechanical studies indicated that inhibition of TFEB could affect lysosomal biogenesis and mitochondrial functions, which would be related to alcohol-induced steatosis and liver injury." (PMID 31614437, 2019). "In addition, transcription factor EB (TFEB) is a major regulator of autophagy and lysosome biogenesis and the transcription and protein expression levels of TFEB were decreased in steatosis hepatocytes, which could be ameliorated by ponatinib treatment." (PMID 39840105, 2024). "Notably, human livers with steatosis or NASH exhibit impaired autophagy with reduced nuclear TFEB." (PMID 38978979, 2024). "Within fasting-induced steatosis models, we analyzed 11 experiments from 10 manuscripts that used genetic liver-specific KO models for ATG7, ATG5, TFEB, and FIP200." (PMID 33937257, 2021). "Within nutrient overload steatosis models, 13 different experiments were analyzed from 9 manuscripts which genetically modulated the expression of ATG7, ATG4B, ATG14, TFEB, FIP200, and ULK1." (PMID 33937257, 2021).
steatosis (continued). "Intriguingly, hepatic mRNA levels of JMJD3, TFEB, ULK1, ATG7, and ATGL, were all decreased in both simple steatosis and advanced NASH-fibrosis patients compared to normal subjects." (PMID 32042044, 2020). "The anti-steatosis effects of CAT may result from activation of AMPK via phosphorylation in liver cells, which in turn increases nuclear translocation of TFEB." (PMID 31697646, 2019). "Additionally, the latest study reveals that XBP1s could activate autophagy through Transcription factor EB (TFEB), which may contribute to glucose tolerance and steatosis in in vivo and in vitro studies." (PMID 35625730, 2022).